TNF (tumor necrosis factor)
Diseases named in the same sentence as TNF in open-access papers (continued):
Sharing a sentence is not in itself a finding about the gene and the disease.
malaria (continued). "Participants with genotype combinations GC/CC/GG/GG and GG/CT/GG/GG (DDX39B-22/DDX39B-348/TNF-308/IL6-176) had decreased and increased risk of mild malaria, respectively, compared with asymptomatic and uninfected participants." (PMID 25038626, 2014). "Both INF-γ and TNF-α play an essential role in the resistance to Plasmodium falciparum (Laveran, 1880): IFN-γ mediates specific immunity to malaria and TNF-α is involved in the rapid clearance of Plasmodium." (PMID 24717449, 2014). "In lethal P. chabaudi malaria, there occurs biphasic, two-wavy increase in serum IL-1β, TNFα, and IL-6 with the first wave peaking on day 1 p.i. and the second wave peaking at maximal parasitemia on day 8 p.i.." (PMID 25408684, 2014). "The aim of this study was to investigate the relationship between TNF-836 C/A and IFN-γ-1616 C/T polymorphism and susceptibility to severe malaria in pregnant women." (PMID 25124540, 2014). "Increased concentrations of IFN-γ distinguished the co-infected from the malaria mono-infected patients in all of the matched groups, whereas significant differences in TNF levels were observed for men only and for patients above 15 years of age." (PMID 24886212, 2014). "Whereas comparable amounts of IFN-γ and TNF were detected in the sera of VL mono- and co-infected patients, the level of these two cytokines significantly raised when malaria patients were co-diagnosed with VL (P <0.001 and P <0.01, respectively)." (PMID 24886212, 2014). "P. falciparum-inducible IFN-γ- and TNF-producing CD4+ T cells also increased after the resolution of malaria compared to baseline, and like IL-10, reverted to homeostasis after the dry season." (PMID 24743880, 2014). "Studies in murine models have shown that TNFα plays an important role in inhibiting the development of hepatic stages of malaria." (PMID 24415936, 2014). "TNF (=TNFalpha or TNFA) and IL-6 are key mediators associated with malaria symptoms, and their levels are increased in proportion to the severity of disease." (PMID 25038626, 2014). "Pro-inflammatory cytokines, especially TNF, IFN-γ and lymphotoxin (LT), have been associated with severe malaria disease and are still crucial for the initial control of parasitaemia in human." (PMID 25124540, 2014). "Clinical malaria cases exhibited an immunological profile qualitatively similar to that of the VL patients, with increased concentrations of TNF, IL-6 and IL-10 (P <0.0001) and, to a less extent, IFN-γ and IL-17A (P <0.01), IL-4 and IL-12p70 (P <0.05)." (PMID 24886212, 2014). "In human clinical trials, although patients did develop CM anti-TNF monoclonal antibody attenuated the malaria fever." (PMID 26430675, 2014). "The beneficial role of TNF in malaria has been demonstrated in animals treated with neutralizing TNF monoclonal antibodies, which prevented clearance of parasitaemia." (PMID 25266106, 2014). "TNF-alpha producing CD4 T cells were independently associated with decreased risk of malaria (OR = 0.63, p value = 0.027) while malaria exposure was associated with increased risk for clinical malaria (OR = 11.24, p value = 0.005)." (PMID 25506706, 2014). "Noticeably, the 1-LOD drop area contained only five genes, and among them, TNF, LTA, and NCR3 have been associated with mild malaria or parasitaemia." (PMID 24884991, 2014). "TNFα production has been shown to correlate with severe malaria, as it is found in higher concentrations in the serum of patients with severe malaria compared to those with mild malaria." (PMID 24550911, 2014). "Circulating levels of interferon (IFN)-γ, interleukin (IL)-2, IL-4, IL-6, IL-10, IL-12p70, IL-13, IL-17A and tumor necrosis factor (TNF) were assessed in sera of patients infected with active VL and/or malaria and healthy individuals from Gedarif State, Sudan." (PMID 24886212, 2014).
malaria (continued). "We quantified production of IFNγ, TNFα, and IL-10 (alone or in combination) by malaria-specific T cells, and analyzed the relationship of this response to past and future malaria incidence." (PMID 24415936, 2014). "In both malaria and coinfected groups the median levels of TNF-α, IL-2, IL-10, IL1-β, MCP-1, and IL-6 were observed to be mostly significantly increased compared with those intestinal parasites and uninfected groups (P < 0.001 for all comparisons)." (PMID 25309052, 2014). "Overall, our data argue that the IFN-γ, TNF-α and MyD88 role on hypersensitivity to septic shock during malaria is, at least in part, mediated by inflammasome-dependent release of IL-1β." (PMID 24453977, 2014). "A large body of literature indicates that in addition to parasite sequestration, inflammatory responses mediated by cytokines such as TNF, IFN-γ and IL-1β are associated with disease severity in human malaria." (PMID 24476686, 2014). "Previous in vitro studies have shown that IL-10 suppresses the expression of malaria parasite-induced production of TNF by PBMC." (PMID 24041406, 2013). "In the group of individuals who survived severe malaria, TNF, IL-4 and direct bilirubin seemed to have a distinguished pattern of connections, albeit, no clear clusters were evident and there was overall low connectivity between the markers studied." (PMID 23433077, 2013). "Variations in several host genes (HBB, IL4, IL12, TNF, LTA, NCR3 and FCGR2A) have been reported to be associated with malaria outcome." (PMID 24066864, 2013). "The cytokine balance seems to influence malaria outcome, with TNF, IFN-γ and IL-10 emerging as key players in both experimental models and in human observational studies." (PMID 23433077, 2013). "Higher plasmatic levels of IFN-γ and IL-10 as well as lower TNF levels were observed in both malaria and individuals infected with P. vivax than control individuals." (PMID 24041406, 2013). "Women with suppressed immune system due to HIV- infection are more likely to develop severe clinical malaria and other opportunistic illnesses, which can favor overproduction of cytokines such as Tumor Necrosis Factor alpha (TNF-α)." (PMID 24007344, 2013). "In humans, TNF-α production during the acute phase of malaria similarly predicts a more rapid clinical and parasitological cure." (PMID 24130857, 2013). "Children also had higher IL-12 (P = 0.0001), IL-4 (P = 0.003), IL-1β (P = 0.024) and TNF (P = 0.006) levels compared to malaria-exposed adults." (PMID 23437061, 2013). "The protective role of TNF-α is suggested by animal studies in which malaria-resistant C57BL/6 mice had higher levels of TNF-α mRNA in the spleen and liver during the early phase of infection, which enhanced clearance of infection." (PMID 24130857, 2013). "TNF-α was associated with IFN-γ, sTNF-RI, SOD-1 and HO-1, implying a potential interplay between those mediators in the pathogenesis of malaria-related symptoms." (PMID 23433077, 2013). "It has been suggested that a reliable predictor of malaria severity is comparison of the ratio between TNF and IL-10 protein levels in the plasma." (PMID 23874969, 2013). "The involvement of TNF in malaria pathogenesis has already been demonstrated in experimental cerebral malaria model." (PMID 24080027, 2013). "We compared the plasma TNF-α and IL-10 concentrations in malaria-infected groups with those in the lupus group." (PMID 24319531, 2013). "In our study, TNF-α levels were similar in malaria patients and HV but a positive correlation between TNF-α levels in serum and phagocytosis index was found." (PMID 23723981, 2013). "In presence of PvMSP-119 stimulus, higher levels of TNF were observed in supernatant 96 h culture of malaria individuals’ cells when comparing with both PSS1 crude antigen (P = 0,03) or without stimulus (P = 0,0006)." (PMID 24041406, 2013).
malaria (continued). "In Gabon, children with a history of severe malaria had fewer T cells producing TNF-α in response to parasite antigen than children with a history of only mild malaria." (PMID 24130857, 2013). "In fact, in the present study, high plasmatic levels of IL-10 and low plasmatic levels of TNF were observed in malaria patients." (PMID 24041406, 2013). "High plasmatic levels of IFN-γ and IL-10 as well as lower TNF levels were also detected in malaria patients." (PMID 24041406, 2013). "The treatment of infected mice with losartan completely blocked malaria-induced production of TNF-α and partially suppressed the increase in IFN-γ in plasma." (PMID 23646169, 2013). "Lentinan induced the enhancement of IL-12, IFN-γ and NO production in spleen cells of malaria infected mice as well as the TNF-α and IL-12 production in bone marrow macrophages and dendritic cells after Listeria monocytogenes infection." (PMID 24223225, 2013). "Endotoxin acts as a potent stimulus for the release of pro-inflammatory cytokines such as TNFα, IL1 and IL6 that have been implicated in the pathophysiology of severe infectious diseases, including malaria." (PMID 23497104, 2013). "Several studies have observed that plasma levels of TNF–α are significantly higher in infected humans presenting with severe malaria." (PMID 24130857, 2013). "The group of subjects with mild malaria displayed a substantial loss of the number of significant interactions in the network and the pro-inflammatory cytokines IFN-γ, TNF and CCL5 had the highest number of connections." (PMID 23433077, 2013). "For instance, in vitro administration of TNF prevents the development of human and rodent malaria pre-erythrocytic stages, but the mechanism of action of TNF against the parasite is unclear." (PMID 24741372, 2013). "In malaria patients, a positive correlation was observed between the levels of TNF obtained from supernatants of cultures stimulated with PvMSP-119 and the time of living in an endemic area (P = 0.001, r = 0.5196)." (PMID 24041406, 2013). "In the present work, lower than expected plasmatic TNF levels (lower than those observed in control individuals) were detected in malaria patients." (PMID 24041406, 2013). "The observation that children had higher levels of TNF and IL-1β in acute phase compared to life-long malaria-exposed adults also suggests a different ability to regulate pro-inflammatory and anti-inflammatory responses according to age and/or exposure." (PMID 23437061, 2013). "As confirmed here, TNF is significantly upregulated in the malaria-infected placenta, and we show for the first time a significant increase in IL-6 expression with PM." (PMID 22347435, 2012). "The IL12RB1AC (−1094/-641) haplotype is only present in the malaria sample whereas the TNF TATGG (−1031/-863/-857/-308/-238) haplotype is 2.5% more frequent in individuals with malaria." (PMID 23217179, 2012). "This phenotypic polarization in the malaria free placentas became altered towards the TNF-α and IL-12-dominated cytokine panel following placental malaria." (PMID 26623293, 2012). "Higher levels of circulating TNF-α were found in adults and children with severe malaria compared to both uncomplicated malaria cases and healthy individuals." (PMID 22745697, 2012). "IL-1β, TNF-α, and IL-12 were previously shown to play important roles in the pathophysiology of malaria and its cerebral form." (PMID 23300448, 2012). "TNF is produced by monocytes and macrophages and its role in malaria pathology was investigated due to reports of high levels of this cytokine in cerebral malaria patients." (PMID 23217179, 2012). "Separately, several TNF-α alleles have been correlated to increased plasma TNF levels, increased susceptibility to severe malaria, and increased susceptibility to cerebral malaria." (PMID 22745697, 2012). "On the other hand, upon stimulation with LPS or Pam, high levels of IL-1β, IL-6, and TNF-α were produced by monocytes from malaria patients." (PMID 22745844, 2012).
malaria (continued). "This is the first report showing NF-κB expression in the PBMCs of malaria patients and its correlation with IL-10 and TNF by using sandwich ELISA." (PMID 22682094, 2012). "In the present study, TNF-α levels in malaria infected placentas were 5 times higher than in malaria free placentas." (PMID 26623293, 2012). "TNF-α levels in plasma samples from malaria infected placentas (88.3 pg/mL) were significantly increased (P < 0.05) compared to levels in plasma samples from malaria negative placentas (17.9 pg/mL)." (PMID 26623293, 2012). "The activation and expression of NF-κB p65 in peripheral blood mononuclear cells (PBMCs) of malaria patients were investigated and correlated with the levels of IL-10 and TNF to study the nature of NF-κB p65 and its linkage to inflammatory cytokines." (PMID 22682094, 2012). "We concluded that JES6-1 treatment enhances the Th1 cell response, leading to increased production of TNF-α and parasite-specific IgG2a antibodies and optimizing the protective immunity to P. chabaudi malaria." (PMID 22272258, 2012). "These include HBB, IL4, TNF, and FCGR2A, which have also been associated with both malaria resistance and IgG levels." (PMID 22947458, 2012). "In this model of malaria, all the inflammatory cytokines (TNFα, IFNγ, IL-1, IL-6, IL-18, IL-10) were found to be significantly elevated in the systemic circulation." (PMID 23323093, 2012). "The linkage or association of HBB, IL4, IL12, TNF, LTA, and NCR3 with mild malaria or parasitaemia has been previously reported in a population living in Burkina Faso." (PMID 22947458, 2012). "TNF-α and IL-12 were detected at significantly (P < 0.05) lower levels in uninfected placentas in comparison with malaria infected placentas." (PMID 26623293, 2012). "9-cis-retinoic acid is a metabolite of vitamin A and an agonist of PPARγ (via RXR ligation), and like rosiglitazone, has been shown to enhance CD36-mediated PE uptake and reduce malaria-induced TNF production in vitro." (PMID 21772838, 2012). "It seems likely that vivax malaria infection was associated with an activation of the pro-inflammatory response and cytokine imbalance and experimental findings in mice are consistent with a role for TNF-a in the dyserythropoietic changes in malaria." (PMID 22624872, 2012). "TNF-α was also previously confirmed as a trigger agent of abortions in the malaria infected primate host." (PMID 26623293, 2012). "UA levels also correlated with IL-6, IL-10, sTNFRII, MCP-1, IL-8, TNFα and IP-10 levels, all of which were elevated in children with severe malaria." (PMID 23071567, 2012). "The present results confirmed high levels of TNF-producing NK cells in acute and severe malaria patients, with CD56bright cells exhibiting the highest production of the cytokine in both infected groups." (PMID 22316273, 2012). "There is substantial evidence that TNF-α is increased and pathogenically involved in both clinical and experimental syndromes of severe malaria." (PMID 23300448, 2012). "SOD-1 is a powerful predictor of malaria severity in individuals infected with P. vivax with higher sensitivity and sensibility than TNF-α levels, confirming the importance of this enzyme in malaria pathogenesis." (PMID 23316245, 2012). "We employed this cell line to assess the role of TNF-α against the hepatic stages of malaria parasites." (PMID 21394207, 2011). "Treatment TNF-α prevents the development of human and rodent malaria pre-erythrocytic stages through the activity of a mediator that remains to be identified." (PMID 21394207, 2011). "Our main finding is that human TNF-α was able to inhibit the hepatic development of two rodent malaria species, P. yoelii and to a lesser extent P. berghei, and most importantly that of P. falciparum." (PMID 21394207, 2011). "In agreement with the known anti-inflammatory properties of NO, malaria-infected mice receiving iNO had lower plasma levels of TNF, IFNγ and MCP-1, inflammatory markers associated with severe malaria." (PMID 22110737, 2011).
malaria (continued). "Specific MAPK pathways have been linked to severe malaria through work on the response of macrophages to P. falciparum GPI, normally resulting in TNF secretion." (PMID 22043276, 2011). "Human or mouse TNF-α were tested against human and rodent malaria parasites grown in vitro in human or rodent primary hepatocytes, or in hepatoma cell lines." (PMID 21394207, 2011). "Multiple comparisons (i.e. 18) have been undertaken to identify the association between TNFα producing CD4+ T cells and protection from clinical malaria." (PMID 21998698, 2011). "As part of the inflammatory cascade, IL-10 is thought to have a suppressive effect on tumor necrosis factor-α (TNF-α), resulting in diminished malaria disease severity." (PMID 21447146, 2011). "Our data demonstrated that TNF-α treatment prevents the development of malaria pre-erythrocytic stages." (PMID 21394207, 2011). "Here, we tested this assumption by quantifying the effects of two well-known innate TBI factors (RNS and TNF-α) on sexual development and fertility of malaria parasites." (PMID 21408620, 2011). "Conversely, a recent study in malaria patients showed a correlation between serum levels of TNF, TNFR2 expression by Tregs, and enhanced Treg suppressive activity." (PMID 20066156, 2010). "TNFα is known to increase erythrophagocytosis and to induce anaemia during malaria both in mouse and in human." (PMID 20618960, 2010). "Those SNP associations with severe malaria are well known and are commonly reported in the literature: CR1, IL4, TNF, G6PD, IL10." (PMID 20459687, 2010). "In agreement with previous findings on P. falciparum and P. vivax infections, individuals with severe malaria displayed higher plasma levels of TNF-alpha than those with asymptomatic parasitaemia or mild disease." (PMID 20386593, 2010). "An extensive analysis was conducted of single nucleotide polymorphisms (SNPs) in the TNF, LTA and LTB genes in highland Papuan children and adults, a population historically unexposed to malaria that has migrated to a malaria endemic region." (PMID 21029472, 2010). "TNF-α promotes parasite killing and has a protective role in controlling parasite levels, but high TNF-α levels have been associated with severe malaria syndromes like severe anemia and cerebral malaria." (PMID 20098675, 2010). "SOD-1 levels were much more effective in predicting vivax malaria severity than TNF-alpha, a major cytokine related to malaria clinical severity in P. vivax infections." (PMID 20386593, 2010). "Proinflammatory cytokines such as TNF-α, IL-1, and IL-6, which are upregulated during malaria, increase HIV proviral expression through the provirus modulatory enhancer region." (PMID 19774084, 2009). "We examined the expression of CD56, membrane-bound IFN-γ and transmembrane TNF-α (mIFN-γ and mTNF-α) in the MO and their major subsets in the peripheral blood of patients with malaria and healthy controls from malaria-endemic areas." (PMID 19851453, 2009). "Malaria-naïve adults experimentally infected with Pf had increased expression of TNF-α, IL-1β and IL-6 in response to a TLR4 ligand (LPS) and IL-6 and IL-10 in response to TLR2 + TLR1 ligand (Pam3Cys) on day 8 of the infection." (PMID 19691558, 2009). "It has been reported that increased concentrations of TNF and IL1β in serum are observed in severe malaria patients." (PMID 19840389, 2009). "High levels of TNF have been shown to result in lethal hepatic damage during blood stage P. chabaudi malaria." (PMID 19341445, 2009). "It has been shown that Kuppfer cells of children chronically exposed to malaria are increased in number and enlarged, and these tissue bound macrophages, if activated, are a possible source of TNFα." (PMID 19149774, 2009). "TNF and ICAM-1 polymorphisms and their association with malaria susceptibility has also been inconsistent across various populations." (PMID 19317913, 2009).